KPNA2 (karyopherin subunit alpha 2)
Diseases named in the same sentence as KPNA2 in open-access papers (continued):
Sharing a sentence is not in itself a finding about the gene and the disease.
tumor (continued). "We found that BMX and FYN had lower expression levels in HCC tumour tissues, whereas KPNA2, PFKFB4, and SPP1 had higher expression levels in HCC tumour tissues." (PMID 36873244, 2023). "KPNA2, a nuclear transporter family member, has been recently shown to promote tumor growth and progression by involvement in cell differentiation, proliferation, apoptosis, immunological response, and viral infection." (PMID 37923899, 2023). "Previous studies have reported that some oncogenic proteins, such as KPNA2, can regulate the tumor infiltration of immune cells." (PMID 36059530, 2022). "Aberrant KPNA2 overexpression is directly correlated with aggressive tumour phenotypes and poor patient survival outcomes." (PMID 35948941, 2022). "KPNA2 removal remarkably suppressed OS cell growth, migration, invasion in vitro, and tumor growth in vivo, while IRF2 knockdown exerts an opposing effect." (PMID 36199790, 2022). "The weakest KPNA1 expression and strongest staining for KPNA2 were observed in grade III tumor tissue." (PMID 35991835, 2022). "Next, we assessed the correlation between the amplification of KPNA2 mRNA expression levels in breast cancer tumours compared to matched healthy breast tissue using Oncomine." (PMID 35948941, 2022). "Specifically, KPNA2 promotes tumour formation and progression through cell differentiation, proliferation and apoptosis." (PMID 36522613, 2022). "Pairwise comparisons of the relative KPNA2 mRNA expression levels were performed in Geneminer according to tumour intrinsic molecular subtype." (PMID 35948941, 2022). "KPNA2 can be induced by hypoxia in various tumour cell types, and its knockdown inhibits osteosarcoma cell proliferation and reduces blood flow." (PMID 36578083, 2022). "KPNA2 expression was detected in the tumor cells and peritumoral fibroblasts, specifically in the nuclei of fibroblasts." (PMID 35884546, 2022). "In conclusion, elevated KPNA2 levels in TSCC are associated with poor prognostic outcomes and tumor grades." (PMID 35860570, 2022). "Our searches of the Geneminer and cBioPortal repositories consistently show that the most frequently-occurring KPNA2 genetic alteration in breast cancer tumours is overexpression." (PMID 35948941, 2022). "For instance, KPNA2, which has been known to enhance BC metastasis ex vivo, is highly expressed in BC tissues (7 out of 12 tumor samples are classified as high)." (PMID 35453681, 2022). "All these data suggested that IGF2BP3 promotes the tumor development of NPC cells by regulating KPNA2 expressions." (PMID 35136045, 2022). "Our integrated analyses of existing datasets indicate that KPNA2 can serve as a prognostic biomarker in breast cancer, warranting further investigation of its biomolecular role in tumour aggressiveness." (PMID 35948941, 2022). "The expression of KPNA1 and KPNA2 in the tumor tissues (n = 106) and adjacent tissues was detected by immunohistochemistry." (PMID 35991835, 2022). "As predicted, knockdown of KPNA2 significantly reduced the tumor burden in the orthotopic xenograft model by using the in vivo imaging system." (PMID 33728352, 2021). "With regards to HCC DFS, tumor stage, KPNA2 CNV, and cg14898140 methylation were presented to be independent prognostic factors for HCC patients, while the prognostic value of KPNA2 expression was not significant." (PMID 34616632, 2021). "Although accumulating evidence confirmed the participating of KPNA2 in the progression of tumour, little is known about the oncogene effects of KPNA2 in ccRCC, as well as its potential effective function for suppression of ccRCC development." (PMID 34469024, 2021). "High KPNA2 expression is positively correlated with tumor differentiation, vascular invasion, and staging in HCC." (PMID 34049287, 2021). "Recent studies also indicated that high expression of KPNA2 was correlated with the development and progression of several tumours." (PMID 34469024, 2021).
tumor (continued). "Based on the RNA‐seq data set from 525 tumour samples, we found the expression level of KPNA2 was significantly higher in clinical stage III/IV patients compared with clinical stage I/II patients." (PMID 34469024, 2021). "In contrast, KPNA2 expression was drastically lower in xenograft tumor tissues from the KDM4A-AS1 silencing group compared to the control group (P < 0.05)." (PMID 34903711, 2021). "In brief, our findings unveiled a critical role of KPNA2 in tumor immune evasion, which indicated that KPNA2 has the potential to serve as a promising biomarker for PDAC patients." (PMID 33728352, 2021). "Different tumor type is a possible explanation; nuclear translocation of KPNA2 in HCC cells resulting in scarce cytoplasm/membrane expression followed by reduced exocytosis is another reasonable interpretation." (PMID 34616632, 2021). "The aim of the present investigation was to unravel the functional role of Karyopherin alpha 2 (KPNA2), a tumor facilitator identified in multiple malignancies, in the progression of BCa." (PMID 33731128, 2021). "For instance, KPNA2 promotes epithelial ovarian carcinoma tumor growth via upregulation of c-myc and downregulation of FOXO3a." (PMID 34903711, 2021). "When adjusted for gender, age, and tumor size, the prognostic effects of KPNA2 (p < 0.001) and NRAS (p < 0.05) also existed, whereas the independent prognostic value of GRB2 was not so significant (p = 0.074, p > 0.05)." (PMID 33193737, 2020). "KPNA2 expression was predominantly observed in the nuclei of tumor cells, with little expression observed in the cytoplasm." (PMID 33176814, 2020). "In this study, we aimed to investigate how radiation increases the levels of KPNA2 in tumor cells and how KPNA2 plays a role in radioresistance." (PMID 31212646, 2019). "And the tumor suppressive effect of miR-139 is partially through down-regulating the expression KPNA2." (PMID 31046781, 2019). "Recently, it has been suggested that cellular stresses, including oxidative stress and heat shock, lead to the nuclear accumulation of KPNA2 in tumor cells." (PMID 31212646, 2019). "Our findings suggested that KPNA2, a potential tumor oncogene, performs its function in part via regulating cellular metabolism through c-myc signaling axis." (PMID 30115078, 2018). "C-Myc depends on the nuclear transporter protein KPNA2 to be translocated into the nucleus, where it is activated and promotes transcription of certain genes, responsible for tumour progression." (PMID 30323892, 2018). "Several studies have identified KPNA2 as a promoter of proliferation in a number of tumour cell lines, whereas the suppression of KPNA2 expression resulted in an anti-proliferative activity." (PMID 30323892, 2018). "As a result, KPNA2, a potential tumor oncogenic protein, performs its function in part via regulating cellular metabolism through c-myc signaling axis." (PMID 30115078, 2018). "Our findings elucidated that KPNA2, a potential tumor oncogenic protein, performs its function in part via regulating cellular metabolism through c-myc signaling axis." (PMID 30115078, 2018). "When the KPNA2-knockdown U87 cells implanted into the right frontal lobes of immunocompromised mice, apparent decrease in tumor formation and subsequent increase in the survival time of the tumor-bearing mice were observed." (PMID 30115078, 2018). "Karyopherin α2 (KPNA2), a member of the Karyopherin α family, has recently been reported to play an important role in tumor progression." (PMID 27974678, 2017). "Accumulating evidences suggest that KPNA2 contributes to the process of regulate genes, including oncogenes and tumor-suppressor genes, thereby affecting the biological characteristics of cells, such as proliferation, apoptosis and etc.." (PMID 27611951, 2016). "KPNA2 expression was higher in 76.1% of tumor samples, compared to their normal tissue counterparts." (PMID 27078844, 2016).
tumor (continued). "Several studies have shown that KPNA2 acts as an oncogene, while others report a tumor suppressor role." (PMID 27078844, 2016). "Statistical analysis the KPNA2 expression between primary tumor and paired normal tissues, showed a significant difference between the two groups (p < 0.001)." (PMID 26626145, 2015). "In contrast, KPNA2 positive staining in primary tumor was significantly higher, with positive staining in 136 (69.7 %) and negative staining in 59 (30.3 %) specimens." (PMID 26626145, 2015). "Studies have shown that KPNA2 appears to play a critical role in arranging cellular proliferation, tumor invasion, and aggressive behavior." (PMID 26626145, 2015). "We conducted a multivariate analysis using the Cox proportional hazard model for all the significant variables in univariate analysis, and the expression of KPNA2 was found to be an independent prognostic indicator to predict tumor recurrence." (PMID 26626145, 2015). "miR-26b/KPNA2 axis suppresses tumor proliferation and metastasis through decreasing OCT4 expression, which is indicative of the important role of miR-26b/KPNA2/OCT4 axis in EOC carcinogenesis and progression." (PMID 26204489, 2015). "In the multivariate Cox regression analysis, only high KPNA2 expression (P = 0.001), male gender (P = 0.002), multiple tumor foci (P = 0.013) and tumor stage(p = 0.022) remained significant." (PMID 25956057, 2015). "We observed that KPNA2 was predominantly stained positively in the nuclei of the primary and lymph node-infiltrated tumor cells, whereas KPNA2 staining was minimally detectable in adjacent normal colon cells." (PMID 26626145, 2015). "According to a univariate analysis, the predictive factors for bladder recurrence were age (P = 0.042), sex (P = 0.014), tumor location (P = 0.007), tumor side (P = 0.046), tumor multiplicity (P = 0.001), tumor stage (0.039) and KPNA2 expression (P = 0.001)." (PMID 25956057, 2015). "Some studies have indicated that higher KPNA2 expression in tumor cell nuclei shortens patient survival, although the mechanisms and precise roles of KPNA2 in the tumor cells remained unclear." (PMID 24098495, 2013). "It is unclear, however, if the possible tumor-promoting activity of KPNA2 is due to its function as a nuclear transporter for selective immunoregulatory proteins such as STAT1 and interferon-γ-induced transcription factor IRF-1." (PMID 23536776, 2013). "KPNA2 expression also correlated with the tumor (T) stage, where the percentage of positive cells increased from T1 through T4 (T1: 6.4%, T2: 10%, T3: 20.6% and T4: 25.4%)." (PMID 23536776, 2013). "Notably, it has been shown that the expression of KPNA2 is upregulated in different types of malignant tumors, and its abnormal expression is generally associated with a poor prognosis in patients, indicating that KPNA2 may play an important role in oncogenesis and tumor progression." (PMID 41413918, 2025). "CAFs, key players in the tumor microenvironment, enhance tumor growth by secreting cytokines and remodeling the extracellular matrix, indicating that KPNA2 may drive tumor progression through CAF modulation." (PMID 39956902, 2025). "In addition to hepatic differentiation markers, the expression of tumor-associated markers (GPC3, SPP1, SPINK1, and KPNA2) was examined across all cell models." (PMID 40862732, 2025). "Finally, in vitro experiments were conducted to explore the functional roles of the key hub gene KPNA2 in telomere maintenance, tumor growth, and metastasis in HCC." (PMID 40665355, 2025). "Furthermore, we validated KPNA2 as a key regulator of telomere maintenance and tumor progression in HCC, suggesting it as a potential therapeutic target for improving clinical management of HCC." (PMID 40665355, 2025). "By regulating KPNA2, miR‐20a‐5p not only affects cancer cell proliferation and migration but may also influence tumour progression through interactions with multiple signalling pathways." (PMID 40830912, 2025).
tumor (continued). "This elevated KPNA2 expression is associated with more aggressive tumor characteristics, including larger tumor size, higher grades, negative hormone receptor status, triple-negative phenotypes, and increased lymph node metastasis." (PMID 40002266, 2025). "Given the critical role of telomere maintenance in regulating tumor cell proliferation and invasion, we investigated its involvement in KPNA2-mediated HCC progression by treating HCC cells with the telomerase inhibitor BIBR1532, a well-characterized small molecule inhibitor of telomerase." (PMID 40665355, 2025). "Blocking IL-10 boosts anti-tumor immunity, and IL-10 may upregulate KPNA2, promoting tumor growth; KPNA2 knockout impairs these processes." (PMID 40443668, 2025). "KPNA2 normally expresses itself at a low level in normal tissues, but in some carcinomas, it has been shown to be overexpressed, which can affect the immune system, tumor cell proliferation, and differentiation." (PMID 38735911, 2024). "Corresponding readout indicates differential KPNA2 expression patterns across the sub-phenotypic classifications, with normal breast-like tumours consistently exhibiting (statistically significant, P < 0.0001) lower KPNA2 expression levels in comparison to other molecular sub-phenotypes." (PMID 35948941, 2022). "These rescuing effects of IRF2 on KPNA2 were also reflected in tumor growth in vivo." (PMID 36199790, 2022). "This may be the reason for the opposite trends in KPNA1 and KPNA2 expression in the same tumor cell line." (PMID 35991835, 2022). "Furthermore, KPNA2 knockdown inhibited the proliferation, migration, and invasion in two OS cell lines, and remarkably reduced tumor weight and tumor volumes in vivo." (PMID 36199790, 2022). "Although KPNA2 has received the most interest of late as a potential target for cancer therapy, it is still controversial as to whether the inhibition of KPNA2 has visible effects on tumor cells." (PMID 35991835, 2022). "KPNA2 may mediate nuclear transport of tumour suppressors, and its up-regulation is closely related to all kinds of malignant tumours." (PMID 36522613, 2022). "To investigate whether IRF2/KPNA2 expression is correlated with other molecular alterations in OS, we evaluated several molecules that are associated with EMT in tumor progression." (PMID 36199790, 2022). "KPNA2 is highly expressed in BC tissues (7 out of 12 tumor samples are classified as high)." (PMID 35453681, 2022). "In vivo, KPNA2 knockdown markedly reduced tumor weight and tumor volumes while IRF2 knockdown promoted tumor growth, and IRF2 knockdown could weaken KPNA2 knockdown-medicated tumor growth inhibition." (PMID 36199790, 2022). "This is in contrast to the trend of KPNA2 expression in tumor tissues." (PMID 35991835, 2022). "KPNA2, a confirmed tumor promoter in a variety of cancers, gained our attention." (PMID 35136045, 2022). "Moreover, the incidence of KPNA2 overexpression has correlated with oestrogen receptor-negative (ER-) status and rapidly proliferating subtypes, specifically basal-like tumours." (PMID 35948941, 2022). "Recent studies have found that KPNA2 is localized on the surface of various tumour cell types." (PMID 36578083, 2022). "KPNA2 expression levels were found to be markedly higher in tumor tissue (83.33%, 25/30)." (PMID 33552715, 2021). "Among the KPNA2 protein variants, the canonical full-length KPNA2 protein (UniProt_P52292) is significantly upregulated in HCC nuclei but is rarely presented in nuclei of non-tumor liver tissues." (PMID 34616632, 2021). "When the four differentially expressed transcripts were applied to multivariable Cox regression analysis with gender, age, and tumor stage as variates, tumor stage and the full-length KPNA2 coding transcript ENST00000330459 independently showed unfavorable prognostic significance for HCC OS and DFS." (PMID 34616632, 2021). "Silencing of KPNA2 significantly repressed the development of tumour cells in vivo." (PMID 34469024, 2021).
tumor (continued). "Moreover, KPNA2 was overexpressed in HCC tissues compared to corresponding non-tumor tissues and negatively correlated to miR-411-5p while positively correlated to KDM4A-AS1 in HCC tissues." (PMID 34903711, 2021). "Collectively, our results allowed the decipherment of a functional axis whereby KPNA2 assisted the nuclear import of CBX8 to activate downstream effectors by recruiting BCOR to the promoter region of PRDM1, thus highlighting the tumor-promoting properties of KPNA2 in BCa." (PMID 33731128, 2021). "Using GAPDH as a control, KPNA2 in all tumour cell lines was strongly expressed." (PMID 34469024, 2021). "On the other hand, inhibition of CBX8 in T24 cells could counterbalance the pro-tumor effects of KPNA2, suggesting that the oncogenic role of KPNA2 in BCa was dependent on CBX8." (PMID 33731128, 2021). "Furthermore, the level of KPNA2 was robustly higher in xenograft tumor tissues derived from the KDM4A-AS1 overexpression compared to the control group (P < 0.05)." (PMID 34903711, 2021). "Results revealed that tumor volume and weight were significantly enhanced in the presence of oe-KPNA2, whereas KPNA2 and c-FOS expression was upregulated and PRDM1 expression was downregulated accompanied by accelerated cell proliferation and suppressed cell apoptosis." (PMID 33731128, 2021). "Moreover, the number as well as size of tumor lesions in the KPNA2 silencing group was smaller than that in the control group." (PMID 33728352, 2021). "Meanwhile, increasing the expression of NPM1 could attenuate the repression effect of silencing KPNA2 in tumour cells." (PMID 34469024, 2021). "A tumor suppressor role was confirmed for miR-26b-5p, and this effect could at least in part be attributed to KPNA2, a known regulator of OCT4, c-jun, and MYC." (PMID 32512858, 2020). "However, the staining intensity or the range of positive distribution of all the other proteins increased in tumor samples, except for KPNA2." (PMID 31695969, 2019). "We further observed that KPNA2 knockdown leads to reduced tumor cell migration and colony formation of HCC cells, which could be phenocopied by direct knockdown of stathmin." (PMID 31783876, 2019). "As a corollary, regulation of tumor metabolism by KPNA2 may provide an important area for cancer diagnosis and therapeutic intervention." (PMID 30115078, 2018). "The results showed that the proliferative tumor cells tended to express higher amount of KPNA2." (PMID 30115078, 2018). "Recently, cereblon was identified to be the target structure of lenalidomide and pomalidomide, and the subsequent enhanced degradation of cereblon-binding proteins like Ikaros, Aiolos and KPNA2 is responsible for the anti-tumor and immunostimulating effect of lenalidomide and pomalidomide." (PMID 29228683, 2017). "We therefore propose that high KPNA2 expression may have similar prognostic value for other types of tumor." (PMID 27974678, 2017). "Moreover, 81.8% tumor counterparts displayed higher levels of KPNA2 than normal tissues, suggestive of a role as an oncoprotein in GC." (PMID 27078844, 2016). "A few of KPNA2-bind cargo proteins have been reported in the tumorigenicity of tumor cells." (PMID 27611951, 2016). "KPNA2 is a target gene of miR-26b, and its overexpression in response to miR-26b reduction might promote tumor proliferation and metastasis through increasing OCT4 expression." (PMID 26204489, 2015). "KPNA2 may therefore be a tumor marker with utility as a prognostic factor of proliferative activity in skin malignancies, although we have insufficient sample sizes to determine significance." (PMID 24098495, 2013). "Researchers also hypothesized that KPNA2-mediated nuclear transport of proteins necessary for maintaining cell proliferation, such as transcription factors, promote tumor cell growth." (PMID 24098495, 2013). "On the contrary, down‐regulation of KPNA2 may suppress tumor‐promoting cellular phenotypes." (PMID 37792911, 2023).